SOCS1 (suppressor of cytokine signaling 1)
Diseases named in the same sentence as SOCS1 in open-access papers (continued):
Sharing a sentence is not in itself a finding about the gene and the disease.
glioma (9 papers, 2015 to 2024). A benign or malignant brain and spinal cord tumor that arises from glial cells (astrocytes, oligodendrocytes, ependymal cells). "It underscores the feasibility of leveraging SOCS1 as a promising diagnostic and prognostic marker for aggressive gliomas, thus offering novel targets for glioma immunotherapy." (PMID 39654174, 2024). "The signaling pathways associated with high SOCS1 expression in the TCGA glioma samples showed similarity to those in the CGGA database." (PMID 39654174, 2024). "This positions SOCS1 as a promising candidate for novel immunotherapeutic interventions, and as a potential diagnostic and prognostic biomarker for glioma patients." (PMID 39654174, 2024). "By conducting functional enrichment analysis, both from differential expression and gene set variation analysis (GSVA) perspectives, we aim to corroborate the association between SOCS1 expression and immune functionality in glioma patients." (PMID 39654174, 2024). "Analysis of glioma mutation data from the TCGA database indicated that the high SOCS1 expression group had a higher tumor mutation burden to some extent." (PMID 39654174, 2024). "Further, it assessed the potential of SOCS1 to refine the accuracy of personalized predictive models, serving as a diagnostic and prognostic indicator for the clinical pathology and survival outcomes in glioma patients." (PMID 39654174, 2024). "Furthermore, identifying SOCS1 as a viable diagnostic marker for aggressive gliomas improves the accuracy of prognostic predictions for affected patients." (PMID 39654174, 2024). "Furthermore, risk scores using a differential expression of SOCS1 as a positive regulatory risk feature demonstrate high predictive accuracy and validity, significantly enhancing the precision of diagnostic and prognostic models for glioma patients." (PMID 39654174, 2024). "In summary, the biological function of SOCS1 in glioma, its expression within the immune microenvironment, and its correlation with immune cells are similar to most immune checkpoints." (PMID 39654174, 2024). "The prognostic value of SOCS1 in predicting glioma patient survival status and clinical features was evaluated using ROC curves." (PMID 39654174, 2024). "This correlation suggests that high SOCS1 expression contributes to the suppression of immune responses against gliomas." (PMID 39654174, 2024). "Comparative analyses within these groups demonstrated that SOCS1 expression was significantly enriched in high-grade gliomas and gliomas with wild-type IDH within the CGGA database." (PMID 39654174, 2024). "This was done alongside a comparison of the similarities between SOCS1 and various glioma immune checkpoints." (PMID 39654174, 2024). "Our findings highlight SOCS1’s potential as an innovative target for glioma immunotherapy, providing a novel strategy to overcome the immunological barriers posed by gliomas." (PMID 39654174, 2024). "Further analysis, incorporating SOCS1 and clinical features of glioma patients into both univariate and multivariate Cox regression models, established SOCS1 as a positive, independent prognostic factor." (PMID 39654174, 2024). "Stromal, immune, and ESTIMATE scores, and tumor purity, were assessed for glioma samples classified into high and low SOCS1 expression groups within the CGGA and TCGA databases." (PMID 39654174, 2024). "This study seeks to bridge this gap through a pan-cancer analysis of SOCS1, investigating its expression patterns within gliomas using public single-cell sequencing data." (PMID 39654174, 2024). "Evaluations using ROC, time ROC, and Kaplan–Meier curves assessed SOCS1’s effectiveness in discerning and forecasting glioma patients’ pathological characteristics and survival outcomes." (PMID 39654174, 2024). "In glioma samples from the CGGA database, the biological processes most closely associated with SOCS1 include 3 main areas." (PMID 39654174, 2024).
glioma (continued). "Assessments of the immune blockade response to 3 checkpoints (PDCD1, CD274, and PDCD1LG2) and the IC50 for 2 classical antitumor drugs were conducted for glioma samples with varying SOCS1 expression levels in the CGGA and TCGA databases." (PMID 39654174, 2024). "Division of TCGA database glioma samples by the median expression of SOCS1 into high and low groups facilitated the construction of a risk profile." (PMID 39654174, 2024). "The TCGA glioma samples to analyze differences in gene expression in the database, the sample is divided into SOCS1 high expression and low expression group." (PMID 39654174, 2024). "To explore the expression of SOCS1 within the glioma immune microenvironment, we investigated its correlation with glioma immune scores." (PMID 39654174, 2024). "Subsequent incorporation of SOCS1 into both univariate and multivariate Cox proportional hazards models, alongside clinical characteristics of glioma patients, demonstrated that SOCS1 acts as a positive prognostic factor in the univariate analysis." (PMID 39654174, 2024). "To delve deeper into SOCS1’s expression within gliomas, we analyzed single-cell sequencing data from the CGGA and GEO databases (GSM5608485) using the Seurat package (version R 4.3.1)." (PMID 39654174, 2024). "A comparison of tumor samples from the TCGA database with normal samples from the GTEx database showed that SOCS1 is more higher expression of SOCS1 in gliomas than in normal tissues." (PMID 39654174, 2024). "Increasing SOCS1 expression appears to simultaneously induce ferroptosis and improve radiotherapy sensitivity, and SOCS1 is a possible therapeutic target for glioma." (PMID 36072803, 2022). "In GBM and glioma cases carrying IDH1 mutations, SOCS1 and SOCS3 methylation was increased and their expression was downregulated." (PMID 32931454, 2020). "We found that primary glioma patients with higher-than-median expression levels of either SOCS1, SOCS3 or RNF7 had an unfavorable prognosis compared to those with lower-than-median expression levels (P < 0.0001)." (PMID 32931454, 2020). "Time ROC curves further validated the efficacy of SOCS1 in forecasting glioma patient outcomes, showing the highest accuracy at the third year with an AUC of 64.0% in the CGGA database and 85.2% in the TCGA database, indicating peak predictive precision at this timeline." (PMID 39654174, 2024). "Further investigation into SOCS1’s expression in gliomas, using single-cell sequencing data from the CGGA and GEO databases, indicated that SOCS1 predominantly accumulates in tumor cells and T cells, exhibiting a similar expression pattern to immune markers such as CD8A and IL7R." (PMID 39654174, 2024). "GSEA enrichment analysis pinpointed the signaling pathways implicating SOCS1 in glioma patients, indicating that high SOCS1 expression in the CGGA glioma samples correlates with allograft rejection, programmed cell death, IL-6 and JAK-STAT3 signaling pathways, and interferon-gamma responses." (PMID 39654174, 2024). "This study conducted a comparative analysis of SOCS1 and glioma immune checkpoints." (PMID 39654174, 2024). "This study, therefore, undertook an analysis of gene sequencing data and patient clinical information to explore and confirm the biological functions of SOCS1 in gliomas, its expression within the immune microenvironment, and its utility in prognostic predictions for patients." (PMID 39654174, 2024). "Studies have shown that tumour-conditioned medium (TCM) collected from the supernatant of human primary glioma cells can upregulate the expression of suppressor of cytokine signalling 1 (SOCS1) in DCs and then inhibit the NF-κB signalling pathway, thereby limiting the maturation of DCs." (PMID 38130720, 2023). "However, SOCS1 is involved in a complex regulatory network, and the role of SOCS1 in inducing ferroptosis in glioma cells is currently less known." (PMID 36072803, 2022).
glioma (continued). "We demonstrated that elevated expression levels of either SOCS1 or SOCS3 could independently predict poor prognosis of patients with primary glioma or GBM." (PMID 32931454, 2020). "Furthermore, we showed that the transcription of SOCS1 and SOCS3 is downregulated in IDH1-mutated glioma cases via methylation, suggesting IDHs mutations can regulate protein turnover." (PMID 32931454, 2020). "This suggests that SOCS1 could serve as a potential target for immunotherapy in glioma patients." (PMID 39654174, 2024). "Pearson correlation analysis between SOCS1 expression and enrichment scores of 13 immune or inflammatory functions obtained through GSVA analysis in the CGGA and TCGA databases revealed that SOCS1 expression is linked to the proliferation and apoptosis of T cells and CD8 in glioma." (PMID 39654174, 2024). "In addition, the negative feedback modulating effect of SOCS1 on IGF-1R mediated signaling has been reported and whether SOCS1 can negatively inhibit IGF-1R signaling in gliomas is worthy of further study." (PMID 38665430, 2024). "Through the analysis of clinical features of 1343 glioma patients from the TCGA and CGGA databases, SOCS1 emerged as a promising marker for the prognosis and prediction of high-grade gliomas." (PMID 39654174, 2024). "Suppressor of cytokine signaling 1 (SOCS1), belonging to the SOCS protein family and playing a pivotal role in various cancer treatment strategies and is abundant in high-grade gliomas." (PMID 39654174, 2024). "Scatter plots illustrate the correlation between SOCS1 expression and stromal scores, immune scores, ESTIMATE scores, and tumor purity in glioma patients." (PMID 39654174, 2024). "The investigation revealed considerable similarities between SOCS1 and several immune checkpoints such as CTLA4, demonstrating SOCS1’s role as an independent prognostic factor positively influencing glioma patient outcomes." (PMID 39654174, 2024). "Pan-cancer analysis conducted with the TCGA database demonstrated a positive correlation between SOCS1 expression and TMB and MSI in certain cancers, and a significant positive correlation with immune scores in most cancers, including gliomas." (PMID 39654174, 2024). "CIBERSORT estimated the abundance and proportion of 22 types of immune cells in glioma samples from the CGGA and TCGA databases, comparing high and low SOCS1 expression groups." (PMID 39654174, 2024). "The ssGSEA method assessed immune cell infiltration in glioma samples from the CGGA and TCGA databases, categorized by SOCS1 expression levels." (PMID 39654174, 2024). "In the Chinese Glioma Genome Atlas (CGGA) dataset, we found that elevated expression levels of SOCS1, SOCS3, TCEB1, TCEB2 and RNF7 correlated with more advanced WHO grades (grades III and IV) of primary glioma." (PMID 32931454, 2020). "A higher-than-median expression level of SOCS1, SOCS3 or TCEB1 also predicts a poor prognosis for WHO grade-IV glioma patients compared to those with lower-than-median expression." (PMID 32931454, 2020). "Additionally, the relationship between SOCS1 and 9 immune checkpoint expressions and stromal, immune, ESTIMATE scores, and tumor purity in glioma patients was analyzed." (PMID 39654174, 2024). "No comprehensive analyses have yet been presented on SOCS1’s expression patterns and its prognostic significance within gliomas." (PMID 39654174, 2024). "By conducting Pearson correlation analysis on glioma samples from the CGGA and TCGA databases, it was discovered that the expression of SOCS1 is significantly positively correlated with several known inhibitory immune checkpoints, including HVEM, TIM-3, PD-1, PDCD2, TIGIT, CD200R1, CTLA4, and CD47." (PMID 39654174, 2024). "Furthermore, the limited number of normal samples paired with glioma patient tumor samples does not allow for further elucidation of SOCS1 expression differences." (PMID 39654174, 2024).
glioma (continued). "Therefore, to assess the impact of SOCS1 activation on immune pathways and cytokine profiles in glioma patients, GSVA analysis was employed to calculate the enrichment scores for immune-related processes in glioma samples from the CGGA and TCGA databases." (PMID 39654174, 2024). "Research findings have suggested a positive correlation between suppressor of cytokine signaling 1 (SOCS1) expression levels and the presence of immune cells such as CD4+ T cells, neutrophils, and myeloid dendritic cells within gliomas, alongside a negative correlation with tumor purity." (PMID 39654174, 2024).
non-small cell lung carcinoma (9 papers, 2016 to 2025). A group of at least three distinct histological types of lung cancer, including non-small cell squamous cell carcinoma, adenocarcinoma, and large cell carcinoma. "In non-small cell lung cancer cells, SOCS-1 inhibits the activity of FAK-dependent signaling pathway, except for JAK/STAT signaling, by suppressing the phosphorylation of FAK tyrosine and promoting polyubiquitination and the degradation of FAK in a SOCS box-dependent manner." (PMID 28228755, 2017). "For instance, lncRNA-HOXC-AS2 regulates TAM polarization through the STAT1/SOCS1 and STAT1/CIITA pathways to promote the progression of non-small cell lung cancer." (PMID 38769475, 2024). "Increased levels of LINC01504 in the non-small cell lung cancers cell lines A549, NCI-H1650, SK-MES-1 and NCI-H226 exposed to cinnamaldehyde promoted the production of cytokine signaling 1 (SOCS1), BTG anti-proliferation factor 2 (BTG2), and Bruton tyrosine kinase (BTK)." (PMID 36499073, 2022).
ovarian carcinoma (9 papers, 2014 to 2024). A malignant neoplasm originating from the surface ovarian epithelium. "Also, it has been reported that the expression level of SOCS1 was significantly increased in human ovarian cancer and might function as a diagnostic biomarker." (PMID 34702300, 2021). "Ectopic overexpression of miR-572 promoted ovarian cancer cell proliferation and cell cycle progression in vitro and tumorigenicity in vivo by inhibiting its direct target suppressor of cytokine signaling 1 and cyclin-dependent kinase inhibitor 1A (p21KIP)." (PMID 30863671, 2019). "The study revealed that the expression of miR-572 inhibited the targets of suppressor of cytokine signaling 1 (SOCS1) and p21 to promote cell proliferation and cell cycle progression of ovarian cancer cell lines, OVCAR3 and SKOV3." (PMID 28800721, 2017). "To evaluate the effects of SOCS1 and p21 on miR-572-induced ovarian cancer progression, we suppressed the expression of endogenous SOCS1 or p21 using specific siRNAs." (PMID 25893382, 2015). "Our study demonstrates that miR-572, which is overexpressed in human ovarian cancer, can target and suppress both SOCS1 and p21, leading to ovarian cancer progression." (PMID 25893382, 2015). "Luciferase reporter plasmids containing regions of the 3` UTR of SOCS1 or p21 were constructed and cotransfected into ovarian cancer cells with miR-572, miR-572 inhibitor or the corresponding negative controls." (PMID 25893382, 2015). "SOCS1 and p21 were identified as direct targets of miR-572 and suppression of SOCS1 or p21 reversed the inhibiting-function of miR-572-silenced cell on proliferation and tumorigenicity in ovarian cancer cells." (PMID 25893382, 2015). "Hypermethylation of the SOCS1 gene has also been observed in breast and ovarian cancer, where SOCS1 reintroduction was again able to suppress cell growth." (PMID 24757565, 2014). "Additionally, the expression of miR-572 correlated inversely with the protein expression levels of SOCS1, p21 and positively with Cyclin D1 in ovarian carcinoma specimens." (PMID 25893382, 2015). "This study demonstrates that miR-572 post-transcriptionally regulates SOCS1 and p21 and may play an important role in ovarian cancer progression; miR-572 may represent a potential therapeutic target for ovarian cancer therapy." (PMID 25893382, 2015). "Furthermore, we demonstrate that miR-572 directly targets and downregulates SOCS1 and p21 via recognizing their 3` UTRs, and downregulation of SOCS1 or p21 was essential for the miR-572-mediated effects in ovarian cancer cells." (PMID 25893382, 2015). "Finally, to examine whether miR-572-mediated suppression of SOCS1 and p21 in ovarian cancer is clinically relevant, seven freshly collected ovarian cancer samples and two normal ovarian tissues were obtained for further study." (PMID 25893382, 2015). "Moreover, the function of miR-572 in ovarian cancer may be exerted via downregulation of the target genes SOCS1 and p21, which play an important role in the function of miR-572 in ovarian cancer." (PMID 25893382, 2015). "Western blotting analysis showed that ectopic expression of miR-572 dramatically decreased, whereas inhibition of miR-572 increased, the protein expression levels of SOCS1 and p21 in both SKOV3 and OVCAR3 ovarian cancer cells." (PMID 25893382, 2015). "All these data showed that ITK could act as a cancer suppressor gene in patients with ovarian cancer and had a similar function to CD244 and SOCS1." (PMID 34702300, 2021).
periodontitis (9 papers, 2013 to 2025). An acute or chronic inflammatory process that affects the tissues that surround and support the teeth. "SOCS1-3 have also been suggested to contribute in the regulation of bone resorption in the context of periodontitis." (PMID 36456933, 2022). "For instance, expression of SOCS1 has been found to be increased in the experimental model of periodontitis, parallel with activation of STAT1 and NF-κB pathways." (PMID 36456933, 2022). "To investigate the mechanisms involved in the protective effects of Pros1 against periodontitis in rats, we evaluated rat periodontal SOCS1/3 and STAT1/3 by Western blot analysis." (PMID 30729671, 2019). "Down-regulation of SOCS1 in the blood samples of patients with periodontitis might lead to up-regulation of several immune-related pathways and molecules which are regulated by this protein." (PMID 36456933, 2022). "SOCS1 showed more hypomethylation in healthy subjects compared to those with aggressive periodontitis, Findings from SOCS1 are interesting because it is a gene that controls inflammation, and thus, its methylation pattern might participate in the development of aggressive periodontitis." (PMID 32867386, 2020). "Another study has detected parallel up-regulation of SOCS1 and IFN-γ in the experimental model of periodontitis." (PMID 36456933, 2022). "Taken together, SOCS1, SOCS2 and SOCS3 genes have been found to be dysregulated in the circulation of patients with periodontitis." (PMID 36456933, 2022). "IL6, IL6R, IFNG, PTGS2, SOCS1, and TNF were identified as candidate genes that have been assessed for DNA methylation in periodontitis." (PMID 32867386, 2020). "A comparison of the DNA methylation pattern of inflammatory regulators SOCS1 and LINE-1 in patients with aggressive periodontitis with healthy individuals showed a higher degree of hypomethylation in oral epithelial cells in healthy subjects." (PMID 29201597, 2017). "Previously, our group analyzed the expression of SOCS1 and SOCS3 in ligature-induced periodontitis in rats." (PMID 24078776, 2013). "Thus, we measured expression levels of SOCS1-3 and SOCS5 transcripts in the blood and gingival samples of patients with periodontitis in comparison with control samples obtained during dental crown lengthening." (PMID 36456933, 2022). "Thus, we measured expression levels of SOCS1-3 and SOCS5 transcripts in the circulation and gingiva of patients with periodontitis in comparison with control samples obtained during dental crown lengthening." (PMID 36456933, 2022). "Interestingly, a previous history of periodontitis did not influence the methylation level of SOCS1, SOCS3, and LINE-1." (PMID 29201597, 2017).